CTLA4 (cytotoxic T-lymphocyte associated protein 4)
Diseases named in the same sentence as CTLA4 in open-access papers (continued):
Sharing a sentence is not in itself a finding about the gene and the disease.
breast carcinoma (continued). "In this study, breast cancer patients were divided into four groups by their CTLA-4 expression profiles in tumor cells and primary TILs." (PMID 25893809, 2015). "In breast cancer, it has been reported to be expressed in both tumour cells and T cells, and an inverse correlation between CTLA4 expression and clinical outcome has been previously reported in 60 patients with different breast cancer subtypes." (PMID 25505134, 2015). "We therefore postulated that the CTLA-4+ dots in cytoplasm of breast cancer cells in the current study contained soluble CTLA-4, apparently synthesized by tumor cells and transported into the tumor microenvironment by transport vesicles." (PMID 25893809, 2015). "In our pre-clinical studies, CTLA-4 blockade acts synergistically with RT to induce an abscopal response to RT in murine models of poorly immunogenic breast cancer and colon cancer." (PMID 25506582, 2014). "It has been previously shown that CXCL16 is responsible for attracting tumor-specific T cells to the irradiated tumor site and is a crucial component of the successful combination of radiotherapy and anti-CTLA4 treatment in a mouse breast cancer model." (PMID 25127546, 2014). "In studies combining CTLA-4 blockade with RT using a mouse model of breast cancer, the antibody was administered at different time-points with the best abscopal response seen when the first dose of antibody was given during RT." (PMID 25506582, 2014). "CTLA-4 expression was detected in breast tissue and blood of breast cancer patients and normal donors." (PMID 23861693, 2013). "In mouse models of breast cancer and colon cancer, growth inhibition of tumors outside the radiation field occurred only when anti-CTLA-4 antibody was given concurrently with fractionated radiation, but not single-dose radiation." (PMID 24403263, 2013). "Clinical research of anti-CTLA-4 in other solid neoplasms like breast carcinoma is scarce until now." (PMID 23861693, 2013). "Using similar mouse models of breast cancer, the abscopal effect resulting from combining radiation and CTLA-4 blockade was abrogated with depletion of cytotoxic T-cells, demonstrating the dependency of the abscopal effect on the immune system." (PMID 24324970, 2013). "One goal of this study was to evaluate the anti-tumor effect of anti-CTLA4 in a mouse model that resembled key features of breast cancer in patients, most importantly tolerance to a TAA (Neu) and the presence of Neu-reactive T-cells." (PMID 21779410, 2011). "We genotyped CTLA-4 variants (-1661 G/A, -658 T/C, -318 T/C, +49 G/A and CT60 G/A) to tag all common haplotypes (≥ 1% frequency) in 117 Chinese breast cancer cases and 148 age/sex matched healthy individuals." (PMID 17825114, 2007). "Thus, ex-vivo approach was used to investigate IL-2 anti-tumor effect on breast cancer cells isolated from Egyptian patients after mastectomy via modulating Treg/CTLA-4/Blimp-1/caspase-3 trajectory." (PMID 42192107, 2026). "Additionally, BRCA1/2-deficient breast cancers have a higher expression of immunosuppressive molecules compared with BRCA1-WT breast cancers in WSI and TCGA cohorts, including CTLA-4, IDO1, and LAG3." (PMID 40830526, 2025). "CTLA4 expression correlates with TIL score and TLS levels (Oslo1 cohort), but no TILlow/CTLA4high patients died from breast cancer, suggesting that the CTLA4 readout identifies low-risk patients not captured by TIL assessment." (PMID 40523912, 2025). "Similarly, CTLA4 expression varies according to the breast cancer subtype, with higher levels in HER2-positive and TNBC BM, suggesting a potential role in immune checkpoint inhibitor therapy." (PMID 41259828, 2025). "However, in some breast cancers, thymomas, esophageal carcinomas, and nasopharyngeal carcinomas, expression of CTLA-4 correlated with poor prognosis." (PMID 38611048, 2024). "The serum levels of HVEM are elevated compared with serum CTLA-4 in breast cancer PBMCs." (PMID 38785930, 2024).
breast carcinoma (continued). "However, in breast carcinoma, contradictory results were seen, as a high level of CTLA-4 mRNA expression correlated with higher stage and lymph node metastasis." (PMID 39286684, 2024). "Additionally, our observations indicated that the expression levels of PSME3 can predict the response to immunotherapy with PDL1 and CTLA4 in gastric adenocarcinoma and breast cancer in mouse models." (PMID 38312840, 2024). "In addition, studies have illustrated that CD4+ T‐cell ICOS expression increases in peripheral blood and tumor tissues of patients treated with anti‐CTLA4 for bladder cancer, breast cancer, and non‐small cell lung cancer." (PMID 38506253, 2024). "Similarly, combining CTLA-4 mAB, PD1 mAB, and cisplatin in BRCA-deficient breast cancer mouse models resulted in synergistic cytotoxicity." (PMID 38956700, 2024). "The expression of immune checkpoint molecules, such as programmed death-ligand 1 (PD-L1) and cytotoxic T-lymphocyte-associated protein 4 (CTLA-4), may modulate the immune response in HER2-positive breast cancer." (PMID 39062682, 2024). "Interestingly, blocking CXCR4 by AMD3100 increased T-cell infiltration in mouse models of breast cancer with high efficacy when combined with anti-PD-1 and anti-CTLA-4 treatments." (PMID 39596815, 2024). "Additionally, a correlation has been observed between GZMA and T-cell checkpoints, including PD-1, PD-L1, and CTLA-4, in breast cancer." (PMID 37760494, 2023). "In addition to its presence on Tregs and T cells, CTLA-4 has also been confirmed to be expressed in the cytoplasm and on the surface of breast cancer cells." (PMID 37860188, 2023). "There are promising prospects for CTLA-4-based breast cancer immunotherapy." (PMID 37860188, 2023). "Cytotoxic T lymphocyte-associated protein-4 (CTLA-4) and other immune checkpoint proteins may be potential prognostic factors and therapeutic targets for breast cancer." (PMID 38406785, 2023). "Clinical trials in evaluating CTLA-4 inhibitors in HER2+ breast cancer are underway." (PMID 37007133, 2023). "Analysis of the Tumor Immune Single Cell Hub (TISCH) database supported these findings by demonstrating that VISTA was highly expressed on immune cells relative to stromal cells and that its expression was significantly more favorable than that of PD-1, PDL-1, and CTLA-4 in breast cancer." (PMID 37152039, 2023). "A pilot clinical study investigating the synergism of cryoablation and pre-operative single-dose ipilimumab (anti-CTLA-4) in early-stage breast cancer patients demonstrated the safety and, importantly, the favorable systemic immunologic and intra-tumoral effects of this combination." (PMID 37686548, 2023). "Furthermore, the Role of CTLA-4 and its immune checkpoint in breast cancer treatment has also demonstrated potential." (PMID 37838657, 2023). "Thus, PD-L1, CTLA-4, GLU, and VIM constitute significant biomarkers in TNBC associated with patients’ outcome, providing new therapeutic targets for this difficult breast cancer subtype." (PMID 37046635, 2023). "Furthermore, the combined therapy of double immune checkpoint inhibitors (ICIs), such as anti-PD1 and anti-CTLA4, with chemotherapy provoked strong systemic and intratumoral immune responses in BRCA1-mutated breast cancer." (PMID 37813891, 2023). "It has been demonstrated that when CTLA-4+ breast cancer cells and human dendritic cells (DCs) are cocultured, the extracellular signal-regulated kinase and activating transcription Factor 3 (ATF3) of DCs are inhibited, thus suppressing the function and maturation of DCs." (PMID 37860188, 2023). "In addition, T cells that invade abemaciclib-treated breast cancer have lower amounts of exhaustion biomarkers such as PD1 and cytotoxic T lymphocyte-associated protein 4 (CTLA4)." (PMID 36768557, 2023). "applied [177Lu]Lu-DOTA-folate and anti-CTLA-4 antibody to mice with breast cancer." (PMID 37860188, 2023). "Next, we comprehensively discuss CTLA-4 inhibitors and their role in breast cancer treatment." (PMID 37860188, 2023).
breast carcinoma (continued). "Most importantly, they directly kill CTLA-4+ breast cancer cells." (PMID 37860188, 2023). "CTLA-4 expression may reflect higher activity of T-Reg cells in patients with breast cancer, which may play a role in tumor establishment and development." (PMID 38406785, 2023). "The combination of anti-CTLA-4 antibody + anti-PD-1 antibody + chemotherapy + PI3K inhibitors may be a novel treatment for breast cancer." (PMID 37860188, 2023). "However, the current use of CTLA-4 inhibitors as monotherapy for breast cancer still faces limitations in terms of response rates and common occurrences of drug resistance." (PMID 37860188, 2023). "introduced anti-CTLA-4 antibody to cocultures of CTLA-4+ breast cancer cells and DCs." (PMID 37860188, 2023). "In recent years, there has been a growing body of research on the efficacy of checkpoint inhibitors with breast cancers, specifically antibodies against cytotoxic T-lymphocyte antigen-4 (CTLA-4), programmed cell death-1 protein (PD-1) and programmed cell death ligand-1 (PD-L1)." (PMID 37860001, 2023). "Briefly, in a breast carcinoma mouse model, dual treatment with fractioned radiotherapy and an anti-CTLA-4 antibody enhanced the abscopal effect, which refers to tumor regression outside the field of radiation due to an indirect systemic anti-tumoral effect induced by radiotherapy." (PMID 37443821, 2023). "Currently, immunotherapy for breast cancer mainly focuses on PD-L1 and CTLA4." (PMID 37351109, 2023). "The study suggests that inhibition of CTLA-4 may improve the action of lymphocytes on breast cancer cells and reduce the proliferation ability of breast cancer cells." (PMID 37860188, 2023). "Blocking the expression of CTLA-4 in HER-2-positive patients with breast cancer may benefit the treatment." (PMID 38406785, 2023). "Moreover, depletion of LDHA in mouse mammary tumors enhanced the therapeutic activity of the CTLA-4 blockade." (PMID 37444501, 2023). "Similarly, fewer lung metastases were found in a prevention study after i.t. injection of a vaccinia virus plus aPD1 and anti-CTLA-4 into MMTV-PyMT mice with mammary carcinomas." (PMID 35118189, 2022). "Previous studies have shown that CTLA-4 expression levels are elevated in breast cancer patients, and the absence of CTLA-4 can cause dysregulation of the immune response." (PMID 35742351, 2022). "In a pilot clinical study examining the safety of preoperative single dose ipilimumab (anti-CTLA-4) and/or cryoablation in 19 women with early-stage breast cancer, not only was the combination safe, favorable intratumoral and systemic immunologic effects were also noted." (PMID 36389815, 2022). "A low CTLA-4 expression was observed in the advanced stages of breast cancer." (PMID 36428664, 2022). "According to their data, a hypofractionated RT, with 24 Gy delivered in three fractions (8 Gy × three fractions), administered every other day of a week, followed by an ICI (i.e., anti-CTLA-4), resulted in an effective therapeutic scheme to switch the cold mammary carcinoma TME into a hot one." (PMID 35877226, 2022). "Additionally, the CAF-S1 FAP+ subpopulation is an important source of CXCL12 secretion, which plays a crucial role in resistance to anti-PD-1 and anti-CTLA-4 immunotherapies in pancreatic, ovarian, and breast cancer." (PMID 35745648, 2022). "In the present study, to better understand the importance of LAG-3 in breast cancer and its interaction and correlation with other immune checkpoints, such as CTLA-4 and PD-1, we evaluated the prognostic significance of LAG-3 by gene-expression analysis in a cohort of 461 breast cancer patients." (PMID 36289918, 2022). "Additionally, LRBA was shown to be involved in trafficking key immune checkpoints (e.g., CTLA-4), is known to contribute to immune dysregulation, and is correlated with both disease mortality and recurrence in breast cancer." (PMID 35660939, 2022).
breast carcinoma (continued). "In addition to studying the effects of combined radiotherapy with anti-CTLA-4 treatments, preclinical studies suggest that radiotherapy and anti-PD-1/L1 therapy synergistically potentiate antitumor immunity in murine breast cancer models." (PMID 36387071, 2022). "Another study has uncovered the inhibition of immune cytotoxicity by NETs via immune cell-target cell contact impairment and inhibition of NETosis by pharmacologically suppressing PAD4 augments tumor sensitivity to PD-1 + CTLA-4 dual checkpoint blockade in a syngeneic mouse model of breast cancer." (PMID 36147630, 2022). "•Anti-PD-1 and anti-CTLA-4 induced anti-tumor response in breast cancer mouse model." (PMID 35339889, 2022). "We also showed by multiplex analysis that mRNA expression levels of compiled CD80/CD86, known receptors of CTLA-4, and PD-L1/PD-L2, known receptors of PD-1, demonstrated improved overall survival of patients with breast cancer, including all subtypes combined and with triple negative breast cancer." (PMID 35339889, 2022). "Breast cancer immunotherapy now focuses primarily on PD-L1 and CTLA4." (PMID 35739182, 2022). "Almost two decades ago, preclinical results from a model with poor immunogenic metastatic mouse mammary carcinoma demonstrated an increased survival when the CTLA-4 blockade was combined with RT, which correlated with the inhibition of lung metastases formation." (PMID 36612206, 2022). "Furthermore, later studies suggest that fractionated radiotherapy—as opposed to single-dose radiotherapy—induces systemic antitumor effects in combination with anti-CTLA-4 treatment in murine breast cancer models." (PMID 36387071, 2022). "Due to a systematic review, four studies involving two studies on rectal cancer, a study on breast cancer, and another single study on esophageal cancer have evaluated the changes in the expression level of CTLA-4 in the TME after CRT or NCT alone until January 2019." (PMID 35967381, 2022). "However, in some tumor models such as murine adenocarcinoma TSA breast cancer, the fractionated protocol was more effective than the single-dose protocol at inducing the abscopal effect when combined with anti–CTLA-4 therapy." (PMID 33669885, 2021). "Anti-CTLA-4 combination with metronomic chemotherapy has also been tested in breast cancer." (PMID 34729098, 2021). "CTLA-4 is an encouraging therapeutic way to boost anti-breast cancer immunity." (PMID 33724757, 2021). "As curcumin diminished PD-L1 expression in cancer cells, antitumor immunity was improved, and cancer cells were sensitized to anti-CTLA-4 therapy in multiple animal models (including breast cancer), bringing to light the role of curcumin as an adjuvant to immune checkpoint therapies (ICT)." (PMID 33572626, 2021). "It was shown that the presence of CTLA-4 on tumor cells is associated with a poor prognosis in breast cancer patients (HR 2.820, p = 0.007), however, there are no definite results from the ongoing clinical trials of anti-CTLA-4 antibodies in the TNBC subtype." (PMID 34885122, 2021). "Here, we demonstrate a novel combinatorial treatment modality where we obtain a relatively high survival rate in mice with aggressive metastatic breast cancer using photothermal therapy with the SWCNT-ANXA5 bioconjugate combined with anti-CTLA-4-based checkpoint inhibition." (PMID 33411055, 2021). "Thus, further experiments would be crucial to carefully consider the therapeutic anti-tumor potential of CTLA-4 modulation in the context of breast cancer treatment." (PMID 34440813, 2021). "Also, some studies indicate that breast cancer patients with higher CTLA-4 mRNA levels had obvious axillary lymph node metastases and a higher clinical stage." (PMID 33906311, 2021). "In addition, downregulating the expression of TGF-β in tumors by oncolytic adenovirus targeting TGF-β demonstrated enhanced anti-PD-1 and anti-CTLA-4 therapeutic effects in animal models of kidney cancer and breast cancer." (PMID 34877360, 2021).
breast carcinoma (continued). "Furthermore, blockage of CTLA-4 on breast cancer cells led to the restoration of dendritic and T cells activity with concomitant inhibition of cancer cell proliferation." (PMID 34440813, 2021). "The new treatments for breast cancer are also discussed in this article, including the use of PARP, MAPK, CHK1, CDK 4/6 inhibitor, anticytotoxic T-lymphocyte-associated protein 4 (anti-CTLA4) antibodies, and anti-programmed cell death protein 1 (anti-PD1)/ligand 1 (anti-PD-L1) antibodies." (PMID 34198652, 2021). "These patients also had a significant decrease of lymphocytes and increased numbers of functionally suppressive CD4+CD25+ Tregs in the peripheral blood and tumor microenvironment, With a subsequent increase of CTLA4 expression on both T cells and breast cancer cells." (PMID 37305162, 2021). "ICI using anti-CTLA-4+anti-PDL-1 is undergoing clinical evaluation in breast cancer patients." (PMID 33149194, 2020). "Finally, we used data from GEO database to verify the differences of CTLA-4 in different molecular types of breast cancer and related prognostic results." (PMID 33033520, 2020). "Results showed that serum PD-1 and PD-L1 levels were significantly higher in cats with HER2-positive (p = 0.017; p = 0.032) and triple negative (TN) normal-like mammary carcinomas (p = 0.004; p = 0.015), showing a strong positive correlation between serum CTLA-4 and TNF-α levels." (PMID 32481540, 2020). "Compared with other tumors, studies on CTLA-4 inhibitors in breast cancer are still immature." (PMID 33033520, 2020). "In one study, CTLA-4 expression and T cell activation were studied in 1,087 breast cancer patients." (PMID 33033520, 2020). "In early studies in mouse models of metastatic breast cancers, RT combined with an inhibitor of cytotoxic T-lymphocyte associated protein-4 (CTLA-4), a representative negative immune checkpoint, demonstrated a significant survival benefit compared to RT alone." (PMID 32365904, 2020). "This study supported the clinical application of CTLA-4 blockade in breast cancer therapy." (PMID 32316552, 2020). "Thereafter, the expression of CTLA-4 at protein and mRNA levels was demonstrated in breast cancer." (PMID 32850353, 2020). "CTLA-4 is another immune molecule located on the surface of T cells and expressed by regulatory T cells (Tregs), which triggers an inhibitory signal to immune cells, also being targeted in breast cancer treatment." (PMID 32481540, 2020). "In this study, we wanted to know whether the expression levels of PD-1, PD-L1 and CTLA4 were different between two breast cancer clusters." (PMID 32179831, 2020). "However, most of these studies focused on the effect of PD-1 and CTLA4 inhibitors on breast cancer, and the overall response rate (ORR) was relatively low." (PMID 32602545, 2020). "Furthermore, TNF-α is described to be elevated in cats with mammary carcinoma, being positively correlated with serum CTLA-4 levels, as in humans." (PMID 32481540, 2020). "To date, the regulation of CTLA-4 by miRNAs is still poorly understood in breast cancer." (PMID 32316552, 2020). "The higher the density of CTLA-4 in lymphocytes, the lower the expression in breast cancer cells, and the better the prognosis will be 35.However, the relationship between CTLA-4 expression in tumor cells of TNBC patients and prognosis has been rarely reported." (PMID 33033520, 2020). "According to the literature, CTLA-4 is also expressed in a subsample of breast cancer cells and their role in cancer cell responsiveness to ICIs is actually unknown." (PMID 33096896, 2020). "Furthermore, cytotoxic T-lymphocyte-associated antigen 4 (CTLA-4) is another immune mediator that inhibits T-cell immune function, being also targeted in breast cancer." (PMID 32481540, 2020).